FBXO11 (F-box protein 11)
Diseases named in the same sentence as FBXO11 in open-access papers (continued):
Sharing a sentence is not in itself a finding about the gene and the disease.
autism (5 papers, 2020 to 2023). Persistent deficits in social interaction and communication and interaction as well as a markedly restricted repertoire of activity and interest as well as repetitive patterns of behavior. "FBXO11, encoding the F-box only protein 31, shows two recurrent p.Ser831fs LoF variants in autism and congenital hydrocephalus (p=1.9e-3)." (PMID 35666111, 2022). "Among the most affected proteins, FBXO11 has been associated with Neurodevelopmental disorders, mental retardation, and autism." (PMID 35215967, 2022). "FBXO11 is another rare de novo loss-of-function and missense variant in autism and appears in the autism-associated CNV region of 2p16.3." (PMID 34341515, 2021). "Individuals with de novo mutations in FBXO11, an analogous of PRMT10, have been reported to show intellectual disability and autism." (PMID 31915053, 2020).
pancreatic cancer (5 papers, 2019 to 2024). "Several downstream proteins have been discussed to be tumor regulator in pancreatic cancer, such as FBXO11, IL-6 and RBM3 except SLC38A2." (PMID 37005877, 2023). "FBXO11 was able to inhibit tumor cell growth and induced cell death by target BCL-6 for degradation, and deletion or mutation of FBXO11 in pancreatic cancer patients was associated with poor prognosis." (PMID 30341246, 2019). "To determine whether ERK3 also increases Snail protein stability by inhibiting the binding of FBXO11 to Snail in pancreatic cancer cells, we used siRNA to suppress the expression of FBXO11 in MIA PaCa-2 cells, and then expressed ERK3." (PMID 38201533, 2023). "Therefore, we conclude that ERK3 is a key regulator for enhancing Snail protein stability in pancreatic cancer cells by inhibiting the interaction between Snail and FBXO11." (PMID 38201533, 2023). "While our biochemical studies indicate that FBXO11 inhibits the chromatin binding of SAMD1, the precise molecular mechanisms and how FBXO11 influences the biological role of SAMD1 in pancreatic cancer have not been fully elucidated in this study." (PMID 39137238, 2024).
B cell lymphoma (4 papers, 2019 to 2024). "FBXO11 is known to play a critical role in maintenance of B cell levels via the BCL6 pathway and FBXO11 loss of function is frequently observed in B cell lymphoma cell lines and increased B-cell levels, as we observed in the Fbxo11tmb2/+ knockout mouse." (PMID 32117459, 2020). "This is consistent with evidence for human FBXO11 haploinsufficiency, with heterozygous germline de novo loss-of-function alleles found recurrently in children with neurodevelopmental disorders, and with high frequency heterozygous loss-of-function somatic mutations in human B cell lymphoma." (PMID 33914737, 2021). "Restoration of BCL6 function in the B cell lymphoma cell lines has been shown to inhibit B-cell lymphogensis, indicating a potential critical role played by FBXO11 in the modulation of B cell survival." (PMID 32117459, 2020). "The data presented here reveal that AIP is a positive regulator of BCL6 protein expression, which is commonly upregulated in B cell lymphomas, and show that AIP binds to an E3 ligase (FBXO11) and a DUB (UCHL1), both of which have been associated with DLBCL pathobiology." (PMID 31042473, 2019). "FBXO11, through regulation of BCL6, modulates B-cell survival and plays a crucial role in B-cell lymphoma." (PMID 32117459, 2020).
Burkitt lymphoma (4 papers, 2020 to 2026). A rare form of malignant mature B-cell non-Hodgkin lymphoma. "Mutations in FBXO11 have also been identified in 10–20% of Burkitt’s lymphoma and cases of de novo AML, suggesting that it may have a broad role as a tumor suppressor in hematologic malignancies." (PMID 33024076, 2020). "Jude Cloud PeCan database, somatic FBXO11 variants have been detected in eight pediatric oncology patients of whom seven were diagnosed with a Burkitt lymphoma (BL), but none with a DLBCL." (PMID 33811277, 2021).
hepatocellular carcinoma (4 papers, 2019 to 2025). A malignant tumor that arises from hepatocytes. "Reference 1 Shao L, Zhang X and Yao Q (2020) The F-box protein FBXO11 restrains hepatocellular carcinoma stemness via promotion of ubiquitin-mediated degradation of Snail." (PMID 37219057, 2023). "FBXO11 is also a target of miR-21 and miR-26a, and the latter inhibits hepatocellular carcinoma (HCC) cell proliferation and metastasis by suppressing FBXO11." (PMID 31159774, 2019).
Intellectual disability (4 papers, 2020 to 2024). "FBXO11 encodes an F-box protein, and de novo variants have been associated with syndromic intellectual disability and behavioral difficulties, including ADHD35,36." (PMID 38997333, 2024). "De novo mutations on FBXO11 were found to cause intellectual disability with behavior problems as well as facial dysmorphisms and other neurodevelopmental disorders." (PMID 38177348, 2024). "DNMs in FBXO11 have been previously implicated in severe intellectual disability individuals with autistic behavior problem and neurodevelopmental disorder." (PMID 35666111, 2022).
deafness (3 papers, 2015 to 2022). An inherited or acquired condition characterized by the complete loss of the ability to hear from one or both ears. "The Jeff mouse mutant carries a mutation in the Fbxo11 gene, a member of the F-box family, and develops deafness due to a chronic proliferative OM." (PMID 26471094, 2015). "Jeff, Junbo, and edison mutants are COME mouse models each with single point mutation in the Fbxo11, Evi1, and nischarin genes respectively, identified at MRC Harwell through a deafness screen as a part of a larger scale N-ethyl-N-nitrosourea (ENU) mouse mutagenesis program." (PMID 32117459, 2020).
glioma (3 papers, 2015 to 2025). A benign or malignant brain and spinal cord tumor that arises from glial cells (astrocytes, oligodendrocytes, ependymal cells). "A negative correlation between miR-21 and FBXO11 expression has been observed in glioma patients, with higher FBXO11 levels associated with lower tumor grade and improved patient survival." (PMID 40534867, 2025). "MiR-21 is also known to contribute to glioma's resistance to chemotherapy by targeting tumor suppressor genes such as FBXO11 and PDCD4." (PMID 26473373, 2015).
melanoma (3 papers, 2015 to 2025). A malignant, usually aggressive tumor composed of atypical, neoplastic melanocytes. "Notably, FBXO11 acts as a tumor suppressor in melanoma and has been shown to regulate apoptosis of B10BR mouse melanocytes." (PMID 26116372, 2015).
leukemia (2 papers, 2020 to 2026). A malignant (clonal) hematologic disorder, involving hematopoietic stem cells and characterized by the presence of primitive or atypical myeloid or lymphoid cells in the bone marrow and the blood. "How FBXO11 loss affects myeloid cells and contributes to leukemia progression is unclear." (PMID 33024076, 2020). "As there is no known combination of mutants with AML1-ETO that results in human leukemia, we asked whether the combination of AML1-ETO, activated KRAS, and FBXO11 depletion could initiate human leukemia." (PMID 41289019, 2026). "Indeed, the stem cell phenotype induced by FBXO11 depletion is sufficient to cooperate with AML1-ETO and KRASG12D to produce a synthetic serially transplantable leukemia from normal CD34+ cells." (PMID 41289019, 2026). "Importantly, we show that depletion of FBXO11 cooperates with AML1-ETO and activated KRASG12D to generate serially transplantable leukemia in a xenograft model." (PMID 41289019, 2026).
lung adenocarcinoma (2 papers, 2016 to 2024). A carcinoma that arises from the lung and is characterized by the presence of malignant glandular epithelial cells. "Low FBXO11 expression in lung adenocarcinoma cells increases ZEB1 protein levels, decreases epithelial marker E-cadherin, and increases mesenchymal markers N-cadherin and vimentin, promoting EMT and enhancing cell migration and invasion." (PMID 39409891, 2024). "We screened lung adenocarcinoma samples against FBXO11 expression in the TCGA clinical database." (PMID 39409891, 2024). "Our findings elucidate the roles played by FBXO11 and ZEB1 in lung adenocarcinoma from a fundamental molecular perspective." (PMID 39409891, 2024).
microcephaly (2 papers, 2022). A congenital or acquired developmental disorder in which the circumference of the head is smaller than normal for the person's age and sex. "Other researchers have demonstrated the coexistence of neurodevelopmental disorders with benign short or tall stature, obesity, microcephaly, or macrocephaly in the case of de novo variants in the mutation of the FBXO11 F-Box protein." (PMID 35565107, 2022). "Therefore, the alteration of FBXO11 and KIF1A could be associated with microcephaly and Guillain–Barré syndrome that develop during and/or after ZIKV infection." (PMID 35215967, 2022).
myeloid leukemia (2 papers, 2026). A clonal proliferation of myeloid cells and their precursors in the bone marrow, peripheral blood, and spleen. "Consistent with previous studies showing that reduced mitochondrial respiration activates a stem cell program, we found that FBXO11 depletion induced a myeloid-biased, quiescent stem cell phenotype, and, in cooperation with other mutations, induced myeloid leukemia in a human xenograft model." (PMID 41289019, 2026). "FBXO11 depletion cooperates with AML1-ETO and KRASG12D to generate human myeloid leukemia." (PMID 41289019, 2026). "Taken together, these results demonstrate that FBXO11 depletion improves long-term in vivo human cell reconstitution, consistent with induction of a myeloid-skewed, long-term self-renewing stem cell state that cooperates with KRASG12D and AML1-ETO to generate myeloid leukemia." (PMID 41289019, 2026). "In myeloid leukemia cell lines, we found binding of MYC at the FBXO11 promoter but did not observe peaks in undifferentiated embryonic stem cell or lymphoblast lines." (PMID 41542766, 2026).
myeloid malignancies (2 papers, 2020 to 2026). "Strikingly, we also identified 12 mutations that clustered in the N-terminus of FBXO11 — between residues 1 and 56 — including patients with myeloid malignancies (red)." (PMID 41542766, 2026). "Taken together, we have uncovered a functional N-terminal IDR in FBXO11 that is mutated in myeloid malignancies." (PMID 41542766, 2026). "FBXO11 mutations in myeloid malignancies reveal an N-terminal intrisically disordered region." (PMID 41542766, 2026). "Moreover, since prior reports showed that TLR2-TRAF6 activation suppresses oncogenic MYC activity in myeloid malignancies, we tested whether the TLR2 agonist CU-T12-9 reduces MYC’s association with the FBXO11 promoter." (PMID 41542766, 2026). "However, the role of FBXO11 in myeloid malignancies remains unclear." (PMID 33024076, 2020).
vitiligo (2 papers, 2019 to 2024). Generalized well circumscribed patches of leukoderma that are generally distributed over symmetric body locations and is due to autoimmune destruction of melanocytes. "For example, the FBXO11 gene is downregulated in vitiligo patients, and may be related to the loss of the pigment-producing melanocytes." (PMID 31159774, 2019).
Alzheimer disease (1 paper, 2024). A progressive, neurodegenerative disease characterized by loss of function and death of nerve cells in several areas of the brain leading to loss of cognitive function such as memory and language. "Variant rs77969729 on FBXO11 has been linked to Alzheimer’s disease in the UKBiobank." (PMID 38177348, 2024).
anemia (1 paper, 2026). A reduction in the number of red blood cells, the amount of hemoglobin, and/or the volume of packed red blood cells. "To clarify which substrates are more likely to be direct targets of the SCF-FBXO11 complex, we performed co-IP of FBXO11 complexes in F-36P cells, established from a patient with MDS-refractory anemia with excess blasts that had progressed to AML." (PMID 41542766, 2026).
cervical cancer (1 paper, 2024). A primary or metastatic malignant neoplasm involving the cervix. "These opposing roles of SAMD1 and FBXO11 can also be seen for other cancer types, such as thymoma and cervical cancer." (PMID 39137238, 2024).
Chorangioma (1 paper, 2026). "Chorangioma-affected tissue harbored pathogenic COL1A1, FBXO11, and TRIM71 somatic mutations, with elevated Leptin expression and oxidative stress signatures." (PMID 41634840, 2026).
chronic myeloid leukemia (1 paper, 2026). "Accordingly, FBXO11 protein abundance was lower in AML cell lines compared with the chronic myeloid leukemia–derived K562 cell line." (PMID 41289019, 2026).
clear cell renal cell carcinoma (1 paper, 2019). "In the Oncomine database, FBXO11 mRNA levels were lower in normal tissues than in cancer tissues, including clear cell renal cell carcinoma (ccRCC), papillary renal cell carcinoma (pRCC), hereditary ccRCC, non-hereditary ccRCC, VHL mutant ccRCC and VHL wild-type ccRCC." (PMID 31159774, 2019).
developmental delay (1 paper, 2021). "Since the first description of a patient with a FBXO11 alteration and developmental delay in 2016, a total of 71 patients have been published." (PMID 33811277, 2021).
gastric adenocarcinoma (1 paper, 2020). "In our previous study, we identified three miRNAs (hsa-miR-421, hsa-miR-29b-1-5p, and hsa-miR-27b-5p) with two mRNAs (FBXO11 and CREBZF) that might play an important role in the development of gastric adenocarcinoma (GAC) from premalignant adenomas." (PMID 32218690, 2020).
glioblastoma (1 paper, 2019). The most malignant astrocytic tumor (WHO grade IV). "Finally, the ubiquitin ligase activity of FBXO11 destabilizes and inhibits de novo synthesis of HIF-1a, thereby promoting the glioblastoma cell response to hypoxia and inhibiting angiogenesis." (PMID 31159774, 2019).
metastatic cancers (1 paper, 2019). A carcinoma which has spread from the original site of growth to another anatomic site. "Using the microarray datasets in ONCOMINE, we found that FBXO11 expression was lower in normal kidney tissues than in both ccRCC and pRCC, tissues and in primary cancers than in metastatic cancers." (PMID 31159774, 2019).
monocytopenia (1 paper, 2026). "Moreover, in the Nup98-Hoxd13 model, the neutropenia and monocytopenia in Fbxo11-knockdown animals were even worse and were accompanied by striking BM hypercellularity and a reduction in NPM1 protein levels." (PMID 41542766, 2026).
neutropenia (1 paper, 2026). A decrease in the number of neutrophils found in the blood. "In MDS mouse models, genetic ablation of Fbxo11 exacerbated neutropenia concomitant with a profound decrease in NPM1 protein levels." (PMID 41542766, 2026). "Using in vivo murine MDS models driven by RUNX1- or Nup98-Hoxd13, we found that animals with knockdown of Fbox11 had exacerbated neutropenia compared with animals with intact Fbxo11." (PMID 41542766, 2026). "Knockdown of Fbxo11 exacerbates neutropenia in murine models of MDS." (PMID 41542766, 2026). "Taken together, our in vitro and in vivo MDS models exhibited the expansion of FBXO11-low MDS HSPCs and demonstrated their contribution to MDS progression through exacerbated neutropenia." (PMID 41542766, 2026). "We did not see changes in the multipotent stem cell compartment of the BM; however, the Fbxo11+/– mice showed a reduction in immunophenotypically defined granulocyte-monocyte progenitor (GMP) populations, concomitant with significantly worse neutropenia in the periphery." (PMID 41542766, 2026).
non-small cell lung carcinoma (1 paper, 2024). A group of at least three distinct histological types of lung cancer, including non-small cell squamous cell carcinoma, adenocarcinoma, and large cell carcinoma. "Importantly, higher FBXO11 expression is associated with better prognosis in non-small cell lung cancer (NSCLC), highlighting its potential role as a therapeutic target for controlling EMT and cancer metastasis." (PMID 39409891, 2024). "There is a strong association between FBXO11 and ZEB1 in non-small cell lung cancer (NSLC) in a clinical database." (PMID 39409891, 2024).
otitis externa (1 paper, 2022). Inflammation of the anatomical structures of the outer ear and ear canal secondary to an infectious process. "Neither mutants or wild-type littermates had otitis externa at weaning age or as older adults [MecomJbo/+ (P22, n=14; P84, n=12 ears); Mecom+/+ (P22, n=14 ears); Fbxo11Jf/+ (P21, n=13; P57-P223, n=41 ears); Fbxo11+/+ mice (P21, n=10 ears)]." (PMID 35107126, 2022).
pancreatic ductal adenocarcinoma (1 paper, 2024). An infiltrating adenocarcinoma that arises from the epithelial cells of the pancreas.
retinoblastoma (1 paper, 2013). A malignant tumor that originates in the nuclear layer of the retina. "Within the recurrent focal gains or losses in the RbTKO retinoblastoma model, we found 12 in cancer genes, including Lmo1 in 5/6 samples; Ndrg1, Brd4, Fbxo11, and Rbm15 in 4/6 samples; Mdm4, Msi2, and Ezh2 in 3/6 samples." (PMID 23765217, 2013).
uveal melanoma (1 paper, 2021). A melanoma derived from melanocytes of the uveal tract. "A recent study suggested FBXO11 as another E3 ligase responsible for Slug degradation upon MLN4924 treatment in uveal melanoma cells." (PMID 33799604, 2021).